AR (androgen receptor)
Diseases named in the same sentence as AR in open-access papers (continued):
Sharing a sentence is not in itself a finding about the gene and the disease.
Infertility (continued). "This deficiency in SRD5A2 production is suggested to contribute to hybrid infertility by impairing AR signal transduction and disrupting sperm physiology." (PMID 40075943, 2025). "The chronic administration of DHT to female mice from postnatal day 21 generates an androgen receptor-dependent mouse model of PCOS with infertility and metabolic disturbances." (PMID 39761106, 2025). "The gene expression profiles of innate immune response genes, as well as the levels of STING and AR in the blood of infertile men, can serve as predictive indicators of tissue deterioration and the likelihood of successful sperm retrieval." (PMID 38212646, 2024). "The distribution of the different CAG alleles of the AR gene was unimodal in infertile and near to unimodal in fertile individuals, very similar to the symmetric distribution of CAG repeats in infertile patients." (PMID 39596257, 2024). "Some variations in the CAG repeats in exon 1 of the AR gene have been observed in different populations, as well as in fertile and infertile men from different regions." (PMID 39596257, 2024). "In this study, we analyzed the CAGn polymorphic locus of the AR gene in a large cohort of Russian men, comparing infertile individuals with fertile controls." (PMID 39596257, 2024). "Despite developing sex-typical gonads and gonadal hormone production, AR−/− males and females are infertile." (PMID 39419984, 2024). "Depending on the residual activity of the AR, the spectrum of clinical presentation ranges from normal phenotypic females to under-virilized and infertile phenotypic males with gynecomastia." (PMID 39200206, 2024). "Previously, the CAGn polymorphic locus of the AR gene has been studied in fertile and infertile men from the Russian Federation and Ukraine, and in healthy Russian men of different ethnic groups (Slavic, Buryat and Yakut)." (PMID 39596257, 2024). "The relatively high frequency of CAG repeat expansions in the AR gene in infertile male patients suggests the possibility of pre-symptomatic diagnosis of SBMA in these patients." (PMID 39596257, 2024). "The AR gene variant with 21 CAG repeats is the most common in Russian and Ukrainian infertile men and healthy Slavic men." (PMID 39596257, 2024). "The allelic frequency (AF) of the AR gene variants with 21 and 25 CAG repeats was lower in infertile men and higher in the controls (AF 0.1698 vs. 0.2273; p = 0.012, and 0.0744 vs. 0.1189; p = 0.006, respectively)." (PMID 39596257, 2024). "The CAGn polymorphic locus of the AR gene has been studied in infertile men from different populations and countries, but the size of the samples studied has been significantly smaller." (PMID 39596257, 2024). "CEARKO mice develop the same obstructive azoospermia infertility phenotype as the mice having AR knocked out with the Rnase10 Cre." (PMID 36769069, 2023). "For example, altered activation of AR is well known to contribute to lower sperm quality, spermatogenesis, infertility and prostate development." (PMID 35093747, 2022). "For example, the threshold value of the length of AR CAG repeats as 21 triplets is given in the meta-analysis, based on facts that longer alleles are associated with an increased risk of infertility." (PMID 36142533, 2022). "Abnormalities in the AR gene can cause AIS, with phenotypes ranging from CAIS with a complete female phenotype to PAIS with minor degrees of undervirilisation or infertility." (PMID 32345305, 2020). "Overall, the accurate determination of CAG repeats in AR of infertile men, including Klinefelter, should be recommended in clinical practice as it can also predict the risk of developing several tumors." (PMID 32216057, 2020). "Our findings show that the bioinformatics tool HipSTR is 100% accurate in detecting and assessing AR CAG repeats in infertile men (46,XY) as well as in men with low‐level mosaicism." (PMID 32216057, 2020).
Infertility (continued). "Mice in which AR was knocked-out specifically in peritubular myoid cells were azoospermic and infertile." (PMID 29351905, 2018). "Our study shows that the overall infertile population is typical of an increased AR-CAG repeat length." (PMID 26962784, 2016). "The overall infertile patients and azoospermic patients were found to have longer AR-CAG repeat length (standard mean difference (SMD) = 0.19, 95% confidence interval (CI): 0.10–0.28, P < 0.01; SMD = 0.36, 95% CI: 0.10–0.61, P < 0.01)." (PMID 26962784, 2016). "AR-CAG repeat length was longer in infertile men in Asian, Caucasian, and mixed races (SMD = 0.25, 95% CI: 0.08–0.43, P <0.01; SMD = 0.13, 95% CI: 0.02–0.25, P <0.05; SMD = 0.39, 95% CI: 0.15–0.63, P <0.01)." (PMID 26962784, 2016). "One meta-analysis using 33published studies understood correlation betweenCAG repeat number in AR gene and infertility inmen." (PMID 26246877, 2015). "A different genetic abnormality often reported in patients suffering from infertility or PC, are alterations in the CAG repeats in genes encoding the androgen receptor (AR)." (PMID 25837470, 2015). "The metropolitan living environment is both associated with higher serum levels of BPA and MEHP and with an inducing effect on ERs and AR expression in infertile women." (PMID 25268510, 2014). "A strong correlation was found between serum BPA concentration and ERα (r = 0.467; P < 0.0005), ERβ (r = 0.474; P < 0.0005), and AR (r = 0.444; P < 0.0005) expression in infertile women." (PMID 23710174, 2013). "In infertile women, a positive association was found between BPA and MEHP levels and ERα, ERβ, AR, AhR, and PXR expression." (PMID 23710174, 2013). "Our study showed a strong positive correlation between BPA serum concentration and ERα, Erβ, and AR expression both in infertile and fertile groups." (PMID 23710174, 2013). "Given that male cattle–yaks are infertile, we hypothesised that the AR might be involved in fertility impairment." (PMID 40075943, 2025). "In the testis, lack of testosterone or AR causes spermatogenic arrest during meiosis, resulting in infertility." (PMID 36769069, 2023). "In supporting our observations, a pronounced decrease in testosterone levels is considered as a hallmark feature in the aged men, and the lack of AR in Sertoli cells segregates with infertility." (PMID 36929025, 2023). "The current data is insufficient to conclude whether IVF patients who display AR CAG expansion may transfer infertility to their descendants." (PMID 36945970, 2022). "Hence, we are interested in finding the association between the lengths of the CAG and GGC repeats in the AR gene and altered sperm parameters in our population of male subjects with infertility problems." (PMID 36945970, 2022). "This study aimed to evaluate and compare CAG trinucleotide repeat length in the AR gene in fertile and infertile men referred to the infertility treatment center in Yazd province, and examine the relationship between increased repeats and sperm count disorders including OS and AS." (PMID 34723064, 2021). "FKBP52 is an AR chaperone with demonstrated effects in experimental infertile mouse studies." (PMID 34212559, 2021). "Testosterone levels can increase, decrease, or remain normal according to the severity of genetic defects, and impaired androgen receptor is the primary cause of decreased or absent sperm in 40% of infertile men." (PMID 34359947, 2021). "Supplementation with either L. plantarum, inulin, or their combination can prevent infertility caused by T2DM in male rats via improving testicular kisspeptin and AR expression, leydig cell count, and effectively increasing epididymal sperm motility and viability." (PMID 32607132, 2020). "Knockout of AR specifically in Sertoli cells of mice results in azoospermia and infertility." (PMID 29351905, 2018). "AR-CAG repeat polymorphism has been studied for its influence on decreased sexual function, which could lead to infertility." (PMID 26962784, 2016).
Infertility (continued). "This is the first study on GGN repeat of AR gene in infertile male in Khuzestan, Iran." (PMID 26221130, 2015). "Due to the global increasing rate of T2DM and infertility, we aimed to investigate the impact of Lactobacillus plantarum (L. plantarum), inulin, and their combinatory supplementation on fertility markers as well as testicular kisspeptin and androgen receptor (AR)’s expression in diabetic male rats." (PMID 32607132, 2020). "Enhanced MAGEA11 and AR-mediated transcriptional regulation may impact on a correct endometrial decidualisation response, subsequently affecting endometrial receptivity in these infertile women." (PMID 31256208, 2019). "In previous reports, a granulosa cell-specific deletion of Ar gene showed that AR-mediated actions in the granulosa cells are required for the proper follicle dynamics, while excess androgen exposure in the fetal ovaries leads to prevalent hyperandrogenic infertility of polycystic ovary syndrome." (PMID 30840652, 2019). "Thus, dysfunctional ERs and AR signaling due to inappropriate exposure to environmental pollutants may lead to hormonal cancers and infertility." (PMID 26029163, 2015). "Inother word, polymorphism detected in the CAGrichregion of the AR gene may not be a usefulgenetic indication of male factor infertility." (PMID 26246877, 2015). "Indeed, infertile women from metropolitan area presented a significant 10-fold increase, with respect to fertile women, in the gene expression levels of five out of six analyzed NRs, namely ERα, ERβ, AR, AhR and PXR." (PMID 25268510, 2014). "Lycium barbarum caused an up-regulation in the expression of CYP19A1, CYP17A1, AR, and SRD5A2, which in turn increased the level of serum testosterone to combat infertility." (PMID 40149961, 2025). "This study revealed certain differences in the CAGn polymorphic locus of the AR gene in Russian infertile and fertile men and determined the frequency of SBMA in infertile patients." (PMID 39596257, 2024). "In infertile males, PFOS levels were higher than fertile counterparts, together with a higher gene expressions of estrogen receptor (ER) α, ERβ and androgen receptor (AR), suggesting that PFCs activity might be linked also to the genetic expression of sex hormones nuclear receptors." (PMID 30611299, 2019). "This study aimed to explore the number of AR-CAG repeats in 150 fertile controls and 150 idiopathic infertile men, divided into four azoospermia, oligozoospermia, asthenozoospermia, and teratozoospermia subgroups." (PMID 30713477, 2018). "Expression levels of ERα, ERβ, AR, AhR and PXR were significantly higher in infertile subjects from the metropolitan area compared to the other two areas, showing the pattern metropolitan > urban > rural areas." (PMID 26445054, 2015). "The analysis of the correlation between EDs concentration and the NRs expression in blood evidenced that, in both infertile and fertile men, PFOA levels were negatively correlated to the expression of ERα, ERβ, AR, AhR and PXR." (PMID 26445054, 2015). "In particular, BPA and MEHP levels, as well as expression of ERα, ERβ, AR, AhR and PXR were more prevalent in infertile women from the metropolitan area." (PMID 25268510, 2014). "PFOS concentration showed a positive correlation with the expression of AR and PXR only in the infertile group." (PMID 23710174, 2013). "The infertile group showed also significantly higher expression in PBMC of several NRs (ERα, ERβ, AR, and PXR) that regulate endocrine pathways and are also potential EDC targets." (PMID 23710174, 2013). "Although it is not known whether the remaining genes may lead to female infertility, it is noteworthy that in seven of them (ADAD2, AR, C1orf146, MLH3, RAD21L1, SYCP3, and TERB1), the corresponding female KO mice are infertile." (PMID 40896145, 2025). "The study of the CAG polymorphic locus of the AR gene is not mandatory for the genetic evaluation of infertile male and female patients." (PMID 39596257, 2024).
Infertility (continued). "In vivo experiments have shown that sertoli cell-specific AR-knockout mice (S-AR (-/y) mice) are infertile, and almost no sperm are detected in the epididymides." (PMID 34084133, 2021). "Mobasseri and colleagues studied a population of infertile and fertile Egyptian men using polymerase chain reaction and sequencing and found a significant relationship between increased CAG repeats in the AR gene and the development of oligozoospermia (OS) and azoospermia (AS) in infertile men." (PMID 34723064, 2021). "However, we suggest to use NGS panel for the study of AR STR in 46,XY infertile men and men with a suspected low‐level mosaicism." (PMID 32216057, 2020). "The subjects from the metropolitan area are characterized by higher internal levels of BPA as well as gene expression of ERα, ERβ, AR AhR and PXR; moreover, only in this area infertile men had higher BPA and PFOS levels, as well as AhR expression, compared to fertile subjects." (PMID 26445054, 2015). "Indeed, we observed that ERα, ERβ, AR, AhR and PXR expression is correlated positively with BPA levels and negatively with PFOA levels, in both infertile and fertile subjects." (PMID 26445054, 2015). "Moreover, our results point out a panel of NRs (ERα, ERβ, AR, AhR and PXR) induced at the same time in PBMCs of infertile subjects." (PMID 25268510, 2014). "The significantly increased expression of ERα, ERβ, AR, and PXR in infertile women may be a direct consequence of endocrine-related reproductive disorders." (PMID 23710174, 2013). "Such increases in AR expression may potentially lead to functional improvements, suggesting that male cattle–yak infertility is not likely due to the impairment of the AR in the epididymal epithelium." (PMID 40075943, 2025). "Six AR variations were found in eight infertile men affected by non mosaic Klinefelter Syndrome." (PMID 28611373, 2017). "A positive correlation was found also between MEHP and ERα (r = 0.388; P < 0.005), ERβ (r = 0.398, P < 0.005), AR (r = 0.366; P < 0.005), AhR (r = 0.291; P < 0.05), and PXR expression (r = 0.364; P < 0.005) in the infertile group, but not in the control group." (PMID 23710174, 2013).
liver cancer (69 papers, 2013 to 2025). An epithelial or non-epithelial malignant neoplasm that arises from the liver. "Direct linkages have been demonstrated between androgen levels, AR gene polymorphisms, and the progression of hepatitis and cirrhosis to liver cancer." (PMID 40869103, 2025). "This suggests that AR mutations contribute to the metabolic reprogramming and ultimately promotes the development and progression of liver cancer." (PMID 38182647, 2024). "Androgen receptor has been shown to promote hepatitis B virus-induced liver cancer and facilitate Kaposi’s sarcoma-associated herpesvirus (KSHV) infection." (PMID 33915795, 2021). "In addition, the polymorphism of AR (number of CAG repeats) affects liver cancer differently in males and females, which also likely contributes to sex disparities of HCC." (PMID 41228208, 2025). "In addition, our previous study confirmed that Nanog is associated with androgen/AR and plays an important role in the regulation of stemness in liver cancer cells." (PMID 29716628, 2018). "Taken together, it was suggested that AR played a dual role in liver cancer: a promoter in triggering tumorigenesis and a suppressor at advanced stages." (PMID 41228208, 2025). "Conversely, in liver cancer, AR can suppress the metastatic potential of hepatic cancer cells by modulating their migratory behavior and facilitating anoikis." (PMID 40729027, 2025). "Consistent with GTEx data, normal liver tissue and liver cancer showed relatively high AR expression, together with renal pelvis adenocarcinoma." (PMID 41228208, 2025). "To evaluate the malignancy of AR mutations in driving HCC, we compared them with other known single-gene drivers of liver cancer, namely AKT and C-MYC." (PMID 38182647, 2024). "It not only provides insights about the AR gene mutations in HCC but also shows potential diagnostic and therapeutic strategy for liver cancer." (PMID 38182647, 2024). "Conversely, the androgen receptor plays an opposing role: its activation can enhance the replication of the hepatitis virus and promote the expression of genes related to liver cancer development." (PMID 38555602, 2024). "In light of the male predominance in HCC incidence and the role of androgens and AR in oncogenic proliferation, anti-androgen and anti-AR therapies have been tested in the treatment of liver cancer." (PMID 37508414, 2023). "In contrast, PRAME negatively correlated with FOXA2 and AR expression in human liver cancer cell lines." (PMID 37173882, 2023). "In a mouse model of liver cancer, abnormal expression of exosomal miR-92a-2-5p inhibited the translation of the androgen receptor, leading to alterations in the PHLPP/p-AKT/β-catenin signaling pathway and increased invasiveness of liver cancer cells." (PMID 37981718, 2023). "A reduction in AR expression increases the invasion of liver cancer cells by altering PHLPP/p-AKT/β-catenin signaling." (PMID 35185900, 2022). "A previous study showed an increase in miR-92a-2-5p expression in exosomes from macrophages in liver cancer, which directly targets the 3’UTR of the androgen receptor (AR) mRNA to decrease its expression in liver cancer cells." (PMID 35185900, 2022). "Further studies have found that Foxa1 and Foxa2 can mediate and enhance the regulation of ERα or androgen receptor (AR) on target genes during the formation of liver cancer, thereby inhibiting (ERα) or promoting (AR) the development of liver cancer." (PMID 35096574, 2021). "The expression of AR-SV in liver cancer leads to the progress of liver cancer and the resistance to traditional AR antagonists." (PMID 32963562, 2020). "For example, sexual dimorphism in liver cancer is determined by differential target activation depending on Foxa1/2 and AR or ERa interactions." (PMID 31350899, 2019).